RAET1K (retinoic acid early transcript 1K (pseudogene))
Gene: Transcribed unprocessed pseudogene on chromosome 6 (150,000,090 to 150,005,157, reverse strand). Ensembl gene ENSG00000218358.
Diseases named in the same sentence as RAET1K in open-access papers:
RAET1K is named in the same sentence as 5 diseases in open-access papers, as found by Europe PMC text mining. Sharing a sentence is not in itself a finding about the gene and the disease. The quoted sentences say what the papers report.
hepatocellular carcinoma (5 papers, 2020 to 2025). A malignant tumor that arises from hepatocytes. "In addition, the HIF1α/lncRNA Retinoic Acid Early Transcript 1K (RAET1K)/miR-100-5p axis modulates hypoxia-induced glycolysis in hepatocellular carcinoma (HCC) cells and affects HCC progression." (PMID 33652661, 2021).
glioma (4 papers, 2019 to 2022). A benign or malignant brain and spinal cord tumor that arises from glial cells (astrocytes, oligodendrocytes, ependymal cells). "EEF1A1P9 was a protective factor (HR < 1), and ANXA2P2, FER1L4, HILS1, and RAET1K were defined as risk factors (HR > 1) in glioma." (PMID 31681595, 2019). "In our study, we screened out five pseudogenes (ANXA2P2, EEF1A1P9, FER1L4, HILS1, and RAET1K) that were differentially expressed between LGG and GBM and were associated with the prognosis of glioma patients." (PMID 31681595, 2019). "On the contrary, higher expression levels of HILS1 and RAET1K indicate an adverse outcome in glioma." (PMID 31681595, 2019). "In addition, pseudogenes ANXA2P2, EEF1A1P9, FER1L4, HILS1, and RAET1K were found to be significantly correlated with glioma survival." (PMID 33378744, 2020).
tumor (2 papers, 2019 to 2020). "We found that lncRNA retinoic acid early transcript 1K (RAET1K) was upregulated in tumor tissues and were correlated with a poor prognosis of patients with LUAD; further, for the first time, we detected the biological roles of RAET1K." (PMID 32010197, 2019).
infection (1 paper, 2025). The state of being infected such as from the introduction of a foreign agent such as serum, vaccine, antigenic substance or organism. "In contrast, four (ULBP1, EGR3, RAET1K, EGR2) genes were downregulated in uninfected cells (GFP- pHrodo-) relative to the other three infection outcomes." (PMID 40630957, 2025).
RAET1K also shares sentences with these, for which no sentence is quoted: lung adenocarcinoma (1 paper).